CDK6 (cyclin dependent kinase 6)
Diseases named in the same sentence as CDK6 in open-access papers (continued):
Sharing a sentence is not in itself a finding about the gene and the disease.
cancer (continued). "Many of the genes, identified in this study as the potential targets of differentially regulated miRNAs are known to be involved in cancer through their effects on cell differentiation (CDK6, LIFR), apoptosis (PIM1) or hematopoiesis (GATA2, TAL1)." (PMID 20459673, 2010). "Altered expression of CDK6 has been reported in several human cancers." (PMID 41598250, 2026). "In cancer, deregulation of the individual CDKs is linked to different tumor types with high levels of CDK4 being common in sarcoma, glioma and melanoma whereas overexpression of CDK6 is more frequent in hematologic malignancies." (PMID 39966356, 2025). "NETs with an activated CDK4/CDK6-phospho-RB1 pathway may be candidates for cancer therapy with CDK4/CDK6 inhibitors." (PMID 41375037, 2025). "Other targets of phosphorylation of CDK4 and CDK6 may also be of therapeutic interest in cancer, including transcription factors FOXM1, SMAD3 and NFAT4." (PMID 40699853, 2025). "The CDK6 protein is often involved in controlling the G1/S transition of the cell cycle and is overexpressed and hyperactivated in several types of cancer, ultimately promoting uncontrolled cell growth of cancer cells." (PMID 40730655, 2025). "CDK6, which binds to Cyclin D during the G1-to-S phase transition of the cell cycle, plays an essential role in the initiation, growth, and survival of many cancer types." (PMID 40729351, 2025). "CDK6 might also promote alteration of the local microenvironment by interacting in cancer cells with the transcription factor NF-kB, eventually stimulating the production of inflammatory-related cytokines and chemokines." (PMID 39800748, 2025). "This may be an important handicap of these models for the investigation of the role of CDK4 and CDK6 and their inhibition as an anti-cancer strategy, given that, as discussed, inhibitors of CDK4/6 affect immune processes." (PMID 40699853, 2025). "Furthermore, NK cells can deliver let‐7b‐5p to PC cells via exosomes, and by specifically targeting CDK6, it prevents the growth of cancer cells." (PMID 40579785, 2025). "We therefore have tried to summarize below the CDK4 and CDK6 shared activities in cancer progression and at the same time highlighting which are the functions that could be considered specific for each kinase." (PMID 39800748, 2025). "Notably, CDK6 is often upregulated in CDK4/6i-resistant cancers and rapidly proliferating hematopoietic stem cells, underscoring its unique regulatory roles." (PMID 40093074, 2025). "In cancer treatments, CDK2 inhibitors can specifically target CDK2 in cancers where it is a primary driver, minimizing the toxicity and dose limitations associated with inhibiting CDK4 and CDK6." (PMID 40149983, 2025). "In CDK4/6i-resistant cancer cells, CDK6 is often overexpressed." (PMID 40093074, 2025). "Explaining these differences at the conformational level could clarify the shifts towards the CDK6 complex for cell cycle progression in resistant cancer cells, thereby bypassing CDK4/6 inhibition." (PMID 40093074, 2025). "Similarly, miR-218 suppress cancer progression by targeting the 3’-UTR regions of CDK6 and cyclin D1, as demonstrated in gastric cancer studies, indicating a possible analogous mechanism in breast cancer." (PMID 40958878, 2025). "To this end, we first examined the publicly available AML data (gepia.cancer-pku.cn) and found that the CSF1R gene is overexpressed in many AML patient samples, similar to several other AML-implicated targets previously, FLT3, MLL and CDK6." (PMID 38641704, 2024). "Besides testing the kinase mutations CDK6-R31C and CDK4-R24C we generated the murine homolog of p16INK4a displaying the cancer mutation P40L." (PMID 39088265, 2024). "Some cancer proteins such as IGF-1R kinase proteins, CDK-2, and CDK-6 bind to anthocyanidins, namely petunidin, peonidin, malvidin, pelargonidin, delphinidin, and cyanidin, thus anthocyanidins are promising metabolites for the development of cancer drugs." (PMID 39845791, 2024).
cancer (continued). "Notably, cell division protein kinase 6 (CDK6) plays an active role in cell proliferation and differentiation in cancer." (PMID 38668382, 2024). "Notably, these correlations are conserved across human cancer cell lines, where CDK6 expression is positively correlated with CDK4 dependency scores, while showing strong negative correlation with CDK6 dependency scores." (PMID 39617889, 2024). "Furthermore, it has been revealed that CDK6 expression mediates adipogenesis and cancer development through NEDD9, a protein involved in cell invasion, migration, and proliferation." (PMID 38668382, 2024). "Previous studies have demonstrated the crucial involvement of CDK6 in cancer cell proliferation." (PMID 38424516, 2024). "Moreover, our study corroborates emerging data on the immunomodulatory potential of CDK4/CDK6 inhibitors, beyond their well-documented cell cycle arrest capabilities in cancer therapy." (PMID 38383657, 2024). "Our study aims to investigate whether a treatment method other than loperamide, a probiotic agent, S. boulardii, can also be effective in diarrhea associated with malignancy treatment, CDK4 and CDK6 inhibitors are used in this study." (PMID 36945921, 2023). "CDK‐6 is one more key factor in BC due to its crucial role in the development of cancer." (PMID 38107139, 2023). "CDK6 overexpression has been observed in various cancers, like BC." (PMID 38107139, 2023). "Similarly, Indole-3-carbinol showed anti-cancer activity by arresting the cells at G1 phase and inhibiting the expression of cyclin-dependent kinase-6." (PMID 37110494, 2023). "In addition, we identified an anti-cancer role of miR-107 in HCC as a regulator of CDK6 in the cell cycle." (PMID 37744274, 2023). "CDK6 is a long-known critical mediator that promotes the G1 to S transition in the cell cycle; hence, its overexpression is unsurprisingly reported in many types of cancer cells to drive cell division." (PMID 37744274, 2023). "Therefore, the CDK4/CDK6–RB axis is crucial to cell-cycle entry, and the vast majority of cancers destabilize this axis to promote proliferation." (PMID 37190133, 2023). "Collectively, growing evidence demonstrates that targeting CDK4 and CDK6 through CDK4/6 inhibitors might have therapeutic benefits in various cancers and kidney diseases and should be further explored in the future." (PMID 37686364, 2023). "Moreover, together with c-Jun, CDK6 upregulates the vascular endothelial growth factor A (VEGF-A) which is responsible for cancer progression and drug resistance due to its ability to induce angiogenesis." (PMID 37833875, 2023). "Consequently, CDK4 and CDK6 have become prime targets for therapeutic interventions in cancer treatment." (PMID 37593751, 2023). "It should be noted that, according to the information reported by the cBioPortal for cancer genomics, the human RB1 gene, as well as the genes encoding CDK4 (CDK4), CDK6 (CDK6), and cyclin D1 (CCND1), are all expressed in AGS and MCF-7 cells, without mutations reported so far." (PMID 37298236, 2023). "Thus, several common cancer-associated elements were monitored, demonstrating that the patterns of p-AKT, CDK1, CDK6 and PIK3CA were reduced in response to TMED3 depletion." (PMID 36991473, 2023). "CDK6, a cyclin-dependent kinase, is a critical regulator of G1/S transition signaling, and its aberrant activation often leads to uncontrolled cell proliferation and consequently cancer development." (PMID 36498866, 2022). "Due to the intricacy of the function of ribociclib within the MDR cancer cells, specific gene deletion was performed to analyze whether CDK6 could be an effective target for overcoming ABCB1-mediated MDR in cancer cells." (PMID 35459184, 2022). "To study the function of CDK6 expression in pan-cancer, we divided the human pan-cancer samples into high and low expression groups according to the expression levels of CDK6 and we analyzed the enrichment of signal pathways in KEGG and Hallmark in both groups using GSEA." (PMID 35480115, 2022).
cancer (continued). "CDK6 has been found upregulated in a wide range of cancer, including multiple myeloma." (PMID 35197447, 2022). "In particular, CDK6 was chosen for the function “pathway in cancer”, ADAM12 for the function “signaling by EGFR”, HDAC4 was selected for the function “regulation of cell differentiation”, and finally Bcl2 for the function “negative regulation of apoptotic processing”." (PMID 36498866, 2022). "CDK6 has involved cancer progression via (RB)-E2F signaling." (PMID 35720007, 2022). "Therefore, the direct involvement of CDK6 in cell cycle control and proliferation makes it a promising target for the prevention and/or treatment of inflammation-driven cancers and inflammatory diseases." (PMID 36361810, 2022). "Although the nondegradative effects of Fbxo7-mediated ubiquitination of PFKP in T cells remain to be elucidated, we hypothesize an essential role for Fbxo7 in cancer cell lines in blood lineages is as an activator of Cdk6." (PMID 35670764, 2022). "Increased activity of CDK6 is responsible for the metabolic switching in energy consumption pathways, leads to activation of alternative pathways that inhibit the production of reactive oxygen species (ROS), and prevents apoptosis in cancer cells." (PMID 35720007, 2022). "For example, quercetin found in pines, buckwheats, and many other plants has a high binding link through hydrogen bonds to the cyclin-dependent kinase 6 (CDK6) and inhibits its activity, which plays an essential role in the progression of different types of cancer." (PMID 35216475, 2022). "therefore, realizing downregulation of PIK3CA and ABCB1 by knocking out CDK6 in MDR cancer cells overexpressing ABCB1 might benefit combined chemotherapy against cancer cells with ABCB1-mediated MDR." (PMID 35459184, 2022). "The cyclin-dependent kinase 6-phosphoinositide 3-kinase (CDK6-PI3K) signaling axis is an effective target for attenuating ATP binding cassette subfamily B member 1/P-gp-mediated MDR in cancer cells." (PMID 36627891, 2022). "A pan-cancer analysis then confirmed that CDK6 and MET are potential targets upon which T. hemsleyanum may exert antitumor action, especially in ACC, CESC, LGG, and PAAD." (PMID 35480115, 2022). "In addition, CDK6 plays a transcriptional role in tumor angiogenesis and phosphorylates nuclear factor kappa-B (NF-κB), thereby linking cancers to inflammation." (PMID 35720007, 2022). "However, only CDK6 was expressed highly in cancer tissues, which was in agreement with the results obtained from cell line samples." (PMID 35780240, 2022). "In different cancer types, CDK6 may regulate different metabolic enzymes and play distinct roles in glycolysis." (PMID 35241106, 2022). "We hypothesized that selonsertib binding to CDK6 may be a reasonable therapeutic approach toward cancer management." (PMID 35720007, 2022). "Amplification of CDK6 and overexpression of cyclin D protein are also frequent in human cancers." (PMID 34041269, 2021). "What is more, overexpression of miR-34 could reduce the expression levels of MET and CDK6 which have interaction with PI3K/AKT signaling in cancer cells." (PMID 33796457, 2021). "The recent clinical success of the inhibitors of CDK4 and CDK6 has convincingly demonstrated that targeting cell cycle components may represent an effective anti-cancer strategy, at least in some cancer types." (PMID 34204543, 2021). "Among these, CDK4 and CDK6 inhibitors confirmed in clinical trials that CDKs might indeed represent valid therapeutic targets in, at least some, types of cancer." (PMID 34204543, 2021). "Moreover, inhibiting the cell-cycle kinases CDK4 and CDK6 results in a significant therapeutic effect in several cancers." (PMID 33425489, 2021). "We analyzed the prognostic relevance of CDK2, CDK4, and CDK6 genetic alterations and found that CDK4 and CDK6 alterations are associated with low overall survival, disease-free survival, and progression-free survival of cancer cohorts (p < 0.05)." (PMID 33668805, 2021).
cancer (continued). "Among them, Cyclin D1 and CDK6 play a vital role in the G0/G1 phase, therefore the inhibition of Cyclin D1 and CDK6 could be considered as a promising strategy for the treatment of cancers." (PMID 34572904, 2021). "CDK4 and CDK6 inhibitors are now used in clinic for the treatment of patients with estrogen receptor positive metastatic breast cancer and their clinical use is being tested in many other cancer types, alone or in combination with other agents." (PMID 34204543, 2021). "Similarly, recent evidence showed that chemical- or siRNA-based CDK4 and CDK6 inhibition can induce autophagy in multiple cancer cell lines." (PMID 34445095, 2021). "In addition, the I3C-affected CDK6 can regulate cancer cell proliferation both by arresting the cell cycle and involving the transcription of relevant genes." (PMID 33925607, 2021). "CDK6 is a classical oncogene and regulates cell-cycle progression in many types of cancers." (PMID 33589577, 2021). "CDK6, as a cell cycle-dependent kinase and a transcriptional regulator, has been reported to lead to disordered cell cycle regulation and uncontrolled cell proliferation, and plays a crucial role in promoting cancer occurrence and development." (PMID 34530822, 2021). "CDK6 can promote cancer cell proliferation in different types of cancers." (PMID 34322152, 2021). "In OSCC, overexpression of miR-145 dramatically inhibits cancer progression via c-Myc and CDK6." (PMID 34946098, 2021). "Therefore, we conclude that the suppressive effects of CDK4 and CDK6 expression by miR-623 not only affect cancer cell proliferation, but also influence cancer cell migration and invasion." (PMID 32501811, 2020). "Our degraders represent multipurpose tools to study CDK6 biology in even greater detail and may translate to new therapies in cancer." (PMID 33133483, 2020). "Accumulating evidence showed that overexpression or increased activity of CDK6 existed in various types of malignant tumors, which could also act as mediator in the promotion of malignant tumors by other molecules." (PMID 33188661, 2020). "CDK6 as an oncogene has been reported to be overexpressed in cancer cells." (PMID 32767514, 2020). "According to the database of COSMIC, the world's largest and most comprehensive resource for exploring the somatic mutations in human cancer, chromosome 7 consists of lots of well-known cancer-related somatic mutations, including EGFR, BRAF, CDK6, MET, T1F1, and so on." (PMID 32695679, 2020). "Increased CDK6 expression has been found in several human cancer." (PMID 33597968, 2020). "Cyclin D1, a member of the cyclin family (D1, D2, and D3) which functions as a regulatory subunit and forms a complex with CDK4 or CDK6 for regulating cell cycle transition from the G1 to S phase, is frequently overexpressed in cancer cells and dysregulates CDK activity." (PMID 31840737, 2020). "CDK4 and its close homologue CDK6 play a crucial role in various cancer types." (PMID 33255177, 2020). "CDK6 is involved in the (RB)-E2F signaling and subsequently cancer progression." (PMID 32429317, 2020). "And 23 of the 25 functional genes were significantly up-regulated in COAD, such as CDK1, CDK2, CDK4, CDK6, and CDK7, which can cause uncontrolled proliferation and may serve as promising targets in cancer therapy." (PMID 32680494, 2020). "Deletion of CDKN2A made cancer cells more sensitive to a selective activity inhibitor of CDK4/CDK6." (PMID 32860670, 2020). "Additionally, EV RNA sequencing revealed an enrichment of miRNAs, targeting different molecules linked to cancer progression (e.g., cyclin-dependent kinase (CDK) family: CDK2, CDK4, and CDK6) and cancer-survival signalling (PIK3R, RAS, MAPK, and STAT)." (PMID 32942702, 2020). "Palbociclib, a CDK4/CDK6 inhibitor, demonstrated a potent effect in some cancer drugs." (PMID 33597968, 2020). "Palbociclib is an inhibitor of CDK4 and CDK6 approved by the FDA for use in many cancer types." (PMID 32413516, 2020).
cancer (continued). "Together with CDK6 regulates cell metabolism to promote cancer." (PMID 32847129, 2020). "CDK4 and CDK6 are frequently overexpressed and dysregulated in diverse types of cancers." (PMID 30555164, 2019). "Amplification of the oncogenes ERBB2, CDK6, MDM2 affected dependency, as did point mutations in PIK3CA, KRAS, NRAS, VHL and BRAF, validating our approach to highlight genes with significance in cancer." (PMID 30803482, 2019). "A consistent downregulation of CHK1, CHK2, CDK6, and Cyclin D1 was observed, which confirms that cell cycle arrest at the G2/GM phase could be substantial for Lanatoside C treatment to cancer cells." (PMID 31783627, 2019). "Asperchalasine A selectively inhibits cyclin A, cyclin dependent kinase (CDK) 2, and CDK6 in cancer cells to induce significant cell cycle arrest in the G1 phase, suggesting the potential role of asperchalasine A as a promising anti-cancer agent and a selective cell cycle regulator." (PMID 31408989, 2019). "Additionally, it significantly impedes cancer growth and migration via CyclinD1/CDK6 mediated cell cycle G2/M checkpoint arrest." (PMID 31450709, 2019). "This process may change the translation efficiency of the CDK6 mRNA and alter the subsequent reactions that facilitate the development of malignant tumor." (PMID 30829464, 2019). "Although CDK4 and CDK6 have been considered to exert redundant functions in cell cycle regulation, there is accumulating evidence that the two proteins have different functions, particularly in cancer." (PMID 30858922, 2019). "Many of the genes exhibiting higher H3K27me2/3, which can span large chromatin regions, are cancer-associated and include cyclin-dependent kinase inhibitor 2A (CDKN2A) encoding the tumor suppressor p16/INK4A and cell cycle regulator Cyclin-dependent kinase 6 (CDK6)." (PMID 31086012, 2019). "Emerging evidence has revealed that miRNAs are related to several aspects of cancer pathogenesis, including self-renewal, invasion, and metastasis, by targeting cyclin-dependent kinase 6 (CDK6), epidermal growth factor receptor (EGFR), MAPK, and PI3K/AKT signaling pathways." (PMID 30530570, 2019). "Metformin has been shown to block cyclin D1, Cdk4 and Cdk6 in various cancers." (PMID 29765528, 2018). "It is indicated that CDK6 maybe a direct target in the circRNA–miRNA regulatory network of human cancer, and also served as a prognostic biomarker of GC in this study." (PMID 30068360, 2018). "CDK6 inhibition greatly potentiates the anti-cancer effects of AKTi." (PMID 30518851, 2018). "Besides its diagnosis value, CDK6 is also one of the pharmacological targets designated for molecular cancer therapy." (PMID 30123094, 2018). "These discoveries indicate a specific oncogenic role of CDK6 in cancer therapy, which may provide useful information to design the potent anti-cancer drugs with low toxicity." (PMID 29715320, 2018). "RB-E2F signaling pathway is often inactivated in cancer due to various reasons including RB1 loss, RB hyperphosphorylation through increased activity of CDK4/CDK6, or E2F hyperphosphorylation, all of which prevent repression of E2Fs from binding to downstream targets." (PMID 30220967, 2018). "CDK6 could form a complex with Cyclin D and regulate cell progression through the G1 phase of the cell cycle, and expresses high in various cancers." (PMID 29507666, 2018). "Combined inhibition of FLT3 and CDK6 reduced the severeness of cancer-promoting processes, but could still be bypassed by PI3K-mediated signalling involving the nodes PI3K, SHC and AXL resulting in potential treatment escape routes." (PMID 29699481, 2018). "Decreased expression of Ki-67 in DE-EDCP treated 4T1 cells could be the result of G0/G1 cell cycle arrest and increased expression of CDK4/CDK6 inhibitor, p16, as it was previously shown in normal and cancer cells." (PMID 29963272, 2018).